ITFG2 (integrin alpha FG-GAP repeat containing 2)
Description:
As part of the KICSTOR complex functions in the amino acid-sensing branch of the TORC1 signaling pathway. Recruits, in an amino acid-independent manner, the GATOR1 complex to the lysosomal membranes and allows its interaction with GATOR2 and the RAG GTPases. Functions upstream of the RAG GTPases and is required to negatively regulate mTORC1 signaling in absence of amino acids. In absence of the KICSTOR complex mTORC1 is constitutively localized to the lysosome and activated. The KICSTOR complex is also probably involved in the regulation of mTORC1 by glucose.
Synonyms: MDS028; KICS3; FGGAP1
Tractability: PROTAC: ubiquitination databases record sites on it.
Gene: Protein-coding gene on chromosome 12 (2,812,622 to 2,859,791, forward strand). Ensembl gene ENSG00000111203.
Subcellular location: Lysosome membrane
Subcellular location (Human Protein Atlas): Vesicles; Golgi apparatus
Pathways (Reactome):
Cellular responses to stimuli: Amino acids regulate mTORC1
Gene Ontology:
Molecular function: protein binding
Biological process: cellular response to amino acid starvation; cellular response to glucose starvation; negative regulation of TORC1 signaling; regulation of TOR signaling
Cellular component: KICSTOR complex; lysosomal membrane; cytosol; nucleoplasm
Genetic constraint (gnomAD): Loss-of-function variants: 32 observed, 51.87 expected, observed/expected ratio (o/e) 0.62, 90% interval 0.47 to 0.83. The upper end of that interval is the gene's LOEUF score, 0.83, which puts it in group 3 of 6, group 1 being the genes least tolerant of losing a copy. Missense variants: 515 observed, 583.98 expected, observed/expected ratio (o/e) 0.88, 90% interval 0.82 to 0.95. Synonymous variants: 205 observed, 229.38 expected, observed/expected ratio (o/e) 0.89, 90% interval 0.8 to 1.
Homologues: Orthologues: chimpanzee ITFG2 (100% identical), macaque ITFG2 (98% identical), guinea pig ITFG2 (90% identical), mouse Itfg2 (89% identical), dog ITFG2 (89% identical), pig ITFG2 (89% identical), rabbit ITFG2 (88% identical), rat Itfg2 (86% identical), zebrafish itfg2 (68% identical), tropical clawed frog itfg2 (66% identical).
Diseases named in the same sentence as ITFG2 in open-access papers:
ITFG2 is named in the same sentence as 7 diseases in open-access papers, as found by Europe PMC text mining. Sharing a sentence is not in itself a finding about the gene and the disease. The quoted sentences say what the papers report.
Autoimmunity (1 paper, 2024). The occurrence of an immune reaction against the organism's own cells or tissues. "In a lupus mouse model, MRL/lpr, autoimmunity development occurred earlier and was more severe in ITFG2 deficient mice." (PMID 38915393, 2024). "Together, these findings suggest a potential role for ITFG2 in B cell differentiation and as a potential regulator of autoimmunity." (PMID 38915393, 2024).
breast carcinoma (1 paper, 2025).
dilated cardiomyopathy (1 paper, 2020). Cardiomyopathy which is characterized by dilation and contractile dysfunction of the left and right ventricles. "Importantly, three of these genes were validated as ‘diagnostic’ genes given the strong evidence supporting causality derived from our data repository (CAP2-dilated cardiomyopathy, ITFG2-intellectual disability and USP53-liver cholestasis)." (PMID 33083013, 2020).
type 2 diabetes (1 paper, 2025). "Only seven genes had the same direction of effect for comparison of type 2 diabetes samples and healthy samples in all eight datasets: LOC112268118 and MPO had positive logFC, and IL18BP, DELE1, TSPAN32, ITFG2, and NISCH all had negative logFC." (PMID 41465472, 2025).
ITFG2 also shares sentences with these, for which no sentence is quoted: Ataxia (1 paper); Intellectual disability (1); lupus (1).